EPO (erythropoietin)
Diseases named in the same sentence as EPO in open-access papers (continued):
Sharing a sentence is not in itself a finding about the gene and the disease.
myocardial infarction (58 papers, 2008 to 2025). Gross necrosis of the myocardium, as a result of interruption of the blood supply to the area, as in coronary thrombosis. "In adult rats, EPO administration immediately after myocardial infarction reduced infarct size and improved cardiac function linked to neovascularization." (PMID 32038269, 2019). "Erythropoietin (Epo) has been shown to improve myocardial function in models of experimental myocardial infarction, but has also been associated with a rise in thromboembolic events." (PMID 25228850, 2014). "High levels of endogenous erythropoietin in patients with acute myocardial infarction who underwent primary PCI were found to be associated with smaller infarct sizes." (PMID 25228850, 2014). "As a result, the combination of anabolic steroids with erythropoietin may increase the risk of such cardiovascular events as thrombosis or myocardial infarction." (PMID 39584970, 2024). "Moreover systemic application of EPO mobilizes progenitor cells from the bone marrow to the peripheral blood, which was associated with an improved myocardial function after myocardial infarction in mice." (PMID 20849606, 2010). "In animal models, EPO exhibited cardioprotective activity in ischemia-reperfusion injury of isolated adult hearts, and in vivo, in myocardial infarction, long-term EPO treatment induced neovascularization." (PMID 38628440, 2024). "EPO has been found to reduce the area of myocardial infarction in animal experiments during myocardial ischemia-reperfusion." (PMID 37199588, 2023). "More relevantly, the combination G9a inhibitor and erythropoietin was superior to either one alone for protecting myocardium from acute myocardial infarction damage by suppressing the expression of inflammatory, anti-oxidative-stress, anti-ischemic biomarkers." (PMID 35439934, 2022). "Erythropoietin (EPO) increases myocardial performance and induces cardiac repair after myocardial infarction." (PMID 34220518, 2021). "EPO has been shown to limit infarct size and left ventricle remodeling, and to improve cardiac function after myocardial infarction in rodents and pigs." (PMID 34339435, 2021). "In a mouse model of cardiac ischemia-reperfusion injury, erythropoietin stimulated eNOS phosphorylation and NO production in coronary artery endothelial cells lead to the attenuation of myocardial infarct size." (PMID 30235277, 2018). "We assessed the effects of combined polyethylene glycol hydrogel (PEG), human induced pluripotent stem cell-derived cardiomyocyte (iPSC-CM), and erythropoietin (EPO) therapy in a rat model of myocardial infarction." (PMID 28988988, 2017). "Experimental studies testing erythropoietin effects in myocardial infarction mostly used healthy animals and mimicked myocardial ischemia by mechanical injury of the coronary artery." (PMID 28109258, 2017). "Preliminary patient studies suggested the potential of EPO treatment for acute myocardial infarction before or during percutaneous coronary intervention." (PMID 24918289, 2014). "Evidence suggests, EPO treatments protected adult rat cardiomyocytes in-vitro and in-vivo in a rat model of myocardial infarction." (PMID 25237819, 2014). "Nevertheless, our research demonstrates that patients with sleep-disordered breathing tend to have higher EPO levels during acute myocardial infarction." (PMID 23340852, 2013). "Thirty-seven patients undergoing successful primary percutaneous coronary intervention in the acute myocardial infarction have been examined for the levels of EPO, VEGF, and troponin I (Tn)." (PMID 23340852, 2013). "Prolonged EPO therapy after myocardial infarction (MI) in a large animal model was shown to be safe and lead to an increase in viable myocardium, increased vascular density, and was shown to prevent further deterioration of left ventricular function." (PMID 23340852, 2013).
myocardial infarction (continued). "Randomized placebo-controlled trials with EPO in patients with myocardial infarction have been conducted in the Netherlands, Germany, and Japan." (PMID 21943500, 2011). "This study will evaluate novel stem/progenitor cell therapy with combination cytokine treatment of the long-acting erythropoietin analogue, darbepoetin, and granulocyte colony-stimulating factor (G-CSF) in patients with acute myocardial infarction." (PMID 21299845, 2011). "Large-scale clinical trials with a primary endpoint of cardiovascular events are needed to elucidate the efficacy of EPO administration as an adjunctive therapy of myocardial infarction." (PMID 21943500, 2011). "Previous studies mainly examined systemic administration of EPO in experimental myocardial infarction and observed improved survival, cardiac function and enhanced progenitor cell mobilization and homing." (PMID 20849606, 2010). "EPO-mediated angiogenesis significantly improves wound repair, microvascular re-modelling following myocardial infarction and focal cerebral ischaemia." (PMID 20686695, 2010). "In addition, researchers have suggested the important role of the endogenous erythropoietin system in the recruitment of endothelial progenitor cells in hypoxia-induced pulmonary hypertension mice, as well as in patients with acute myocardial infarction." (PMID 39338226, 2024). "Sleep apnea patients have higher levels of serum erythropoietin (EPO) during acute myocardial infarction, and EPO expression is largely controlled by HIF, indicating that sleep apnea may increase HIF activation." (PMID 36174675, 2022). "In studies of isolated adult hearts from rodents, EPO promoted cardioprotection in ischemia reperfusion injury and EPO administration in rabbits was cardioprotective from myocardial infarction." (PMID 32038269, 2019). "SDB patients tend to have higher levels of EPO during acute myocardial infarction." (PMID 23340852, 2013). "Serum EPO levels in patients with myocardial infarction were also investigated." (PMID 23340852, 2013). "Finally, EPO improves the survival of the transplanted eEPCs within the border zone of the myocardial infarction." (PMID 20849606, 2010). "The aim of the present study was to test the hypothesis that in situ expression of recombinant human erythropoietin (rhEPO) would improve tissue repair in rat after myocardial infarction (MI)." (PMID 19014419, 2008). "Moreover, erythropoietin production has been demonstrated after myocardial infarction, which on the basis of our data could be mediated by cardiac HIF activation." (PMID 21811636, 2011). "Although EPO can effectively increase hemoglobin concentration and improve oxygen transport capacity, its abuse may lead to a sharp increase in blood viscosity (HCT>55%), increasing the risk of serious cardiovascular events such as thrombosis and myocardial infarction." (PMID 41195384, 2025). "The key terms employed in the search engines were Myocardial infarction, STEMI, and Erythropoietin/Erythropoietin effects, and the Medical Subject Heading (Mesh) strategy was used mainly in PubMed." (PMID 35812547, 2022). "In acute myocardial infarction (MI) there is an increased myeloid activity, and the inflammatory process correlated with ACS leads to elevated concentrations of erythropoietin and the presence of hematological markers in the peripheral blood." (PMID 34065132, 2021). "Thus, the effort to measure the safety and efficacy of erythropoietin treatment in myocardial infarction patients is still continuing; for instance, the on-going EPAMINONDAS trial is investigating whether erythropoietin treatment can safely reduce infarct size in STEMI patients." (PMID 21299845, 2011). "Recently, a meta-analysis indicated that short-term administration of EPO in the patients with myocardial infarction did not result in an improved cardiac function, reduced infarct size and lower all-cause mortality." (PMID 30911412, 2019).
myocardial infarction (continued). "Myocardial infarction was induced in wild-type mice and EPCs with or without EPO were introduced into myocardium around the infarct." (PMID 25551605, 2014). "No important complications such as myocardial infarction, mean arterial pressure rise, and thromboembolic events were seen in the patients in the EPO group during surgery and in the first postoperative month." (PMID 24644377, 2014). "Different authors have reported that low-dose, but not high-dose, EPO administration improves myocardial infarction in patients with STEMI." (PMID 23348925, 2013). "So far, clinical trials involving erythropoietin treatment in acute myocardial infarction in patients have failed to prove any benefit." (PMID 22649318, 2012). "While increased availability of oxygen carriers may improve oxygen supply to organs and tissues such as the heart and the kidney, administration of EPO in patients with myocardial infarction does not improve outcomes." (PMID 33372185, 2020). "However clinical outcome data more than 12 month after erythropoietin therapy have never been reported in patients treated for myocardial infarction." (PMID 28109258, 2017). "However, the results were disappointing, showing conclusions that EPO did not reduce myocardial infarct size." (PMID 27933299, 2016). "Short-term low-dose' EPO improved cardiac function and infarct size without any clinical adverse effects, but it did not prevent neointimal hyperplasia in percutaneous coronary intervention treated acute myocardial infarction patients." (PMID 25237819, 2014). "Despite the apparent reduction of infarct size and improvement in LV function resulting from EPO treatment in animal models of myocardial infarction, overall these clinical trials did not demonstrate consistent results regarding LV function in the presence of EPO treatment." (PMID 21943500, 2011). "This is supported by a recent report in a model of myocardial infarction in which EPO increased VEGF protein expression and improved revascularisation of the ischaemic myocardium; administration of VEGF-neutralizing antibodies prevented this EPO-mediated enhancement of cardiac revascularisation." (PMID 20686695, 2010). "The study aimed to explore the EPO and VEGF serum levels in SDB and non-SDB patients during the acute phase of myocardial infarction." (PMID 23340852, 2013).
Obesity (55 papers, 2009 to 2025). Accumulation of substantial excess body fat. "This review focuses on the actions of EPO in WAT and the liver, as most studies examining EPO in the context of obesity-associated inflammation in insulin-sensitive organs have concentrated on these two metabolic tissues." (PMID 40697664, 2025). "In conclusion, although differing in molecular mechanisms, EPO exerts anti-inflammatory and metabolic actions in key insulin-sensitive tissues, positioning it as a compelling target in obesity-associated metabolic disorders." (PMID 40697664, 2025). "The longitudinal design of the current study enables, for the first time, the evaluation of time-course changes in EPO levels in obesity after three different weight-loss therapies (VLCKD, LCD and bariatric surgery)." (PMID 38696124, 2024). "In the present study, severe obesity was associated with increased EPO concentrations and iron dysregulation, with a positive correlation with basal weight, FM and FFM in the overall sample." (PMID 38696124, 2024). "In a peritonitis model, treatment of obese mice with recombinant human EPO abrogates the defects in efferocytosis caused by obesity and stimulates inflammation resolution." (PMID 36994095, 2023). "Apart from erythropoietic effects, EPO has regulatory effects upon energy homeostasis, impaired signaling in non‐erythropoietic tissues leading to obesity and IR, and increased EPO levels associated with pre‐eclampsia towards the end of pregnancy." (PMID 35535947, 2022). "Metabolic response to endogenous EPO and elevated EPO in the circulation or brain in mice suggest that EPO improves glucose metabolism and provides regulation of fat mass and inflammation associated with diet induced obesity, especially in males." (PMID 34603036, 2021). "The increased white adipose tissue inflammation and macrophage infiltration associated with diet induced obesity are also reduced with EPO treatment with a shift toward an anti-inflammatory state and decreased inflammatory cytokine production." (PMID 34603036, 2021). "Here we describe the EPO response of cells derived from the monocyte–macrophage lineage such as the anti-inflammatory EPO response during diet-induced obesity in white adipose tissue and brain and the osteoclasts associated with EPO-stimulated bone loss." (PMID 33330462, 2020). "Studies in animal models show that, beyond stimulating erythropoiesis, EPO can also regulate fat mass and monocyte–macrophage-derived cell response in obesity-associated inflammation and bone remodeling." (PMID 33330462, 2020). "We also include a discussion of EPO effects on fat accumulation during diet-induced obesity and on bone marrow stromal cells associated with EPO-stimulated bone loss." (PMID 33330462, 2020). "Our study investigated the mechanism underlying EPO’s anti-obesity and anti-diabetic effects on classical brown adipose tissue (BAT)." (PMID 28288167, 2017). "The effect of background strain on obesity and EPO metabolic response suggests the confounding variability of genetic background not only on susceptibility to obesity but also to metabolic response to EPO." (PMID 24918289, 2014). "We have shown that over-expression of EPO protects against diet-induced obesity and this reduction in weight gain was associated with improvement of metabolic parameters in high-fat fed mice in particular increased fat oxidation in the muscles." (PMID 19521513, 2009). "Other systemic factors include osteoporosis, rheumatoid arthritis (RA), Sjögren’s syndrome, sarcoidosis, hypocalcemia, osteomalacia, Paget’s disease of bone, vitamin D deficiency, erythropoietin therapy, cyclophosphamide therapy, obesity, and alcohol intake, which also elevate the risk of MRONJ." (PMID 40709114, 2025).
Obesity (continued). "All of them are increased in patients with obesity and their concentration in plasma decreases after a weight-loss therapy that improves the metabolic and inflammatory status of patients with obesity, as observed in EPO levels in the current study." (PMID 38696124, 2024). "The metabolic benefit of elevated EPO and EPO induction with increasing altitude may contribute to the reduced incidence of obesity in military recruits in the United States associated with residence at high altitude." (PMID 34603036, 2021). "EPO regulation of metabolism and fat mass in mice may explain in part the association of reduced incidence of obesity in military recruits in the United States (∼94% male) that reside at high altitude." (PMID 34603036, 2021). "In mice, EPO treatment is associated with anti-inflammatory activity, neuroprotection, cardioprotection, skeletal muscle wound healing, protection against diet-induced obesity, and bone loss accompanying EPO-stimulated erythropoiesis." (PMID 33330462, 2020). "Elevation of erythropoietin levels associated with hypoxia due to obstructive sleep apnea whose incidence increases in obesity or cellular hypoxia due to adipose tissue expansion in obese persons may also be possible explanations." (PMID 31836793, 2019). "In conclusion, we have shown that EPO when expressed in supra-physiological levels has substantial metabolic effects including protection against diet-induced obesity and normalisation of glucose sensitivity associated with a shift to increased fat metabolism in the muscles." (PMID 19521513, 2009). "EPO-regulated reduction of lipogenic genes could potentially help reduce fat synthesis that is associated with high triglyceride levels in liver and adipose tissues in metabolic disease or obesity." (PMID 39996752, 2025). "Furthermore, EPO induction at high altitude may account for the inverse association between altitude and obesity observed among US military recruits and among Peruvian adults." (PMID 39284834, 2024). "Thus, this study aims to investigate whether nutritional ketosis and weight loss induced by a VLCKD modify the circulating levels of EPO in patients with obesity in comparison with the effect of low-calorie diet (LCD) or bariatric surgery (BS)." (PMID 38696124, 2024). "The relationship between elevated EPO and reduction in fat mass suggested by metabolic studies in male mice, raises the possibility that increased EPO levels may explain in part the lower obesity rate reported for humans associated with residence at high altitude." (PMID 32038269, 2019). "Experimental data suggest that EPO exerts beneficial effects on hepatic inflammation and glucose metabolism in obesity." (PMID 40697664, 2025). "In the context of diet-related obesity, EPO administration exerts anti-inflammatory effects by inhibiting proinflammatory cytokines and reducing macrophage activity." (PMID 41012526, 2025). "Hypothalamic ventricular administration of EPO in aged obese mice decreased food intake and obesity, improved metabolic function, and reversed impairments in glucose tolerance and insulin sensitivity without increasing hematocrit." (PMID 39996752, 2025). "Recent evidence shows EPO exerts anti-inflammatory effects in insulin-sensitive tissues, thereby improving insulin sensitivity in the context of obesity." (PMID 40697664, 2025). "In contrast, EPO regulation of body weight and fat mass readily observed in male mice exhibits a sex-differential response related to the anti-obesity activity of estrogen in female mice." (PMID 39996752, 2025). "High EPO expression in skeletal muscle, achieved via gene transfer in mice, protected against obesity, reduced fat mass and body weight, and normalized glucose tolerance and fasting insulin levels in high-fat diet-fed mice." (PMID 39996752, 2025).